PINX1 (PIN2 (TERF1) interacting telomerase inhibitor 1 )
Diseases named in the same sentence as PINX1 in open-access papers (continued):
Sharing a sentence is not in itself a finding about the gene and the disease.
cancer (continued). "What is more, in our pre-experiment, we found that hesperidin inhibited cancer cell proliferation with an increase of pinX1 expression." (PMID 35847001, 2022). "Previous studies have shown a correlation between a decrease in PINX1 expression and the metastatic nature and poor prognosis of cancer patients." (PMID 36142793, 2022). "In the previous study, it has been found that pinX1 overexpression in human cancer cells shortens telomeres, induces crisis, and inhibits tumorigenicity, whereas pinX1 depletion plays the opposite role." (PMID 35847001, 2022). "p65 can bind to the PINX1 promoter to inhibit PINX1 transcription, which leads to the increased proliferation of cancer cells." (PMID 33549103, 2021). "Six pDGVs in the PINX1, MOB1A, CLTCL1, PRR5, CCDC136, and TRIM32 genes involved the exact amino acid residues affected by known somatic cancer variants." (PMID 33273457, 2020). "PinX1, a tumor suppressor gene, was previously demonstrated to be a powerful tool for targeting telomerase in order to resist malignant tumor proliferation and migration." (PMID 32028978, 2020). "The overexpression of PinX1 would decrease telomerase activity, thus shortening telomeres, and lower cancer cell tumorigenicity." (PMID 31210926, 2019). "Further eligible studies are needed to determine the prognostic value of PINX1 expression in various types of malignant tumors." (PMID 30079348, 2018). "This is the first meta-analysis to evaluate the prognostic value of PINX1 expression in patients with malignant tumors." (PMID 30079348, 2018). "In this meta-analysis, we showed that low PINX1 expression was associated with significantly poorer OS, DFS/RFS, and clinicopathological characteristics in patients with various types of malignant tumors." (PMID 30079348, 2018). "To date, no meta-analyses have been conducted to determine the prognostic value of low PINX1 expression in patients with malignant tumors." (PMID 30079348, 2018). "We thus investigated the genetic profile and biological implication of PinX1 in several human cancers using the cBioportal database." (PMID 28978030, 2017). "To verify the PinX1 mRNA expression data found in our analysis of past studies in cBioportal for Cancer Genomic, we selected nine types of primary cancer patients’ tissues from our affiliated hospitals." (PMID 28978030, 2017). "The same study also showed that PinX1 contributes to tumorigenicity in cancer cells, in contrast with other studies." (PMID 28815183, 2017). "In other types of cancer, PinX1 expression has been shown to be a predictor of cervical SCC (CSCC) cell response to cisplatin/paclitaxel chemotherapy." (PMID 28815183, 2017). "The expression of PINX1 significantly decreased some human cancers and was correlated to the adverse outcome of cancer patients." (PMID 29371971, 2017). "Nevertheless, our findings provide important contributions to our understanding of PinX1 function in cancer." (PMID 28815183, 2017). "Collectively, our data reveal PinX1 expression patterns and potential mechanisms in various human cancers." (PMID 28978030, 2017). "Previous studies have suggested that PinX1 is an intrinsic telomerase inhibitor and a putative tumour-suppressor gene in human cancers." (PMID 28815183, 2017). "When compared with normal tissue, PinX1 mRNA expression was significantly decreased in most of the selected cancer tissues." (PMID 28978030, 2017). "Our group recently reported that not only does PinX1 contribute to telomerase activity and cancer tumorigenicity but it also increases the sensitivity of cancer cells to DNA damage and chemo-radiotherapy." (PMID 28372542, 2017). "Many studies have shown that PinX1 can regulate telomere maintenance in cancer cells, ultimately inhibiting telomere elongation." (PMID 28978030, 2017).
cancer (continued). "Rather, loss of hetereozygosity seems to play a major role in the inactivation of PinX1 in human cancers." (PMID 28978030, 2017). "Given this, further work will be needed to clarify the mechanisms of PinX1 in regulation of tumorigenesis and the progression of different types of human carcinomas." (PMID 28978030, 2017). "As a major tumor suppressor, PinX1 has been demonstrated to be a new potential target in cancer therapy." (PMID 27556185, 2016). "PinX1 can potently inhibit telomerase activation and telomeres elongation in cancer cells, this ability is also conserved in yeast, rats and zebra fish." (PMID 27556185, 2016). "It seems further works are needed to clarify the mechanisms of PinX1 in regulating tumor genesis and progression of different types of human carcinomas in detail." (PMID 27556185, 2016). "Twenty-four hours or forty-eight hours after transfection, PinX1 proteins were significantly overexpressed or knockdown in ccRCC cancer cells, respectively." (PMID 26033551, 2015). "Then increasing evidences demonstrate that PinX1 plays a key role as a putative tumor suppressor in human cancer progression." (PMID 25888829, 2015). "Forty-eight or twenty-four hours after transfection, PinX1 protein was significantly knockdown or overexpressed in cancer cells, respectively." (PMID 25888829, 2015). "Increasing evidence demonstrate that PinX1 plays a key role as a putative tumor suppressor in human cancer progression." (PMID 25888829, 2015). "PinX1 is a conserved nucleolar protein that has complex roles in telomerase/telomere regulation and cancer." (PMID 24940406, 2014). "Increasing evidence suggests that decreased expression of PinX1 plays a key role in different human cancers." (PMID 24672800, 2014). "The inhibition of endogenous PinX1 in human cancer cells increases the telomerase activity and elongates the telomeres, whereas overexpression of PinX1 inhibits telomerase activity and induces cell crisis." (PMID 24672800, 2014). "In humans, ectopic overexpression of PinX1 leads to a decrease in both telomerase activity and cancer cell tumorigenicity, whereas suppression of PinX1 expression results in an increase in both telomerase activity and cancer cell tumorigenicity." (PMID 24268029, 2013). "PinX1 gene is located on chromosome 8p22-23 region, which has high frequency of loss of heterozygosity (LOH) in a series of human cancer cells." (PMID 22316341, 2012). "The significance of these results is demonstrated by our observations that most PinX1+/- mice develop aggressive cancers that display telomere lengthening and chromosome instability." (PMID 22021332, 2011). "In this study, we demonstrated that TPCH, which derived from LPTS/PinX1, could inhibit the growth of 11 telomerase-positive tumor cells belonging to 9 kinds of immortal human cancer cell lines in vitro, and 3 types of CDX and 2 types of PDX in vivo." (PMID 40896430, 2025). "Then, we used the LPTS/PinX1+/- mice to study the incidence of cancer in these mice." (PMID 40896430, 2025). "LPTS/PinX1, a human liver putative tumor suppressor, could inhibit the cancer cell growth by binding to the hTERT/hTR complex directly." (PMID 40896430, 2025). "We statistically analyzed the level of LPTS/PinX1 protein in 9 cancer cell lines." (PMID 40896430, 2025). "Furthermore, PinX1 deletion significantly correlated with increased cancer stemness and poor prognosis in CESC and even pan-cancer analysis." (PMID 39634130, 2025). "The role of PinX1 in tumorigenesis and progression varies widely among cancer types." (PMID 38431575, 2024). "Differences in the composition of these mechanisms in different cancer cells may also explain the reported paradoxical function of PINX1 in either promoting or inhibiting cancer progression, requiring further research to clarify." (PMID 39174499, 2024).
cancer (continued). "However, studies have also demonstrated PINX1’s involvement in promoting tumor progression in various cancers, raising questions about its exclusive role as a telomerase inhibitor or tumor suppressor." (PMID 39174499, 2024). "Similarly, the inhibitory effect of hesperidin on cancer cell invasion and migration can be canceled by pinX1 siRNA." (PMID 35847001, 2022). "An SCC tissue microarray with 86 cancer samples was stained by the pinX1 antibody." (PMID 35847001, 2022). "Similarly, PIN2/TRF1-interacting telomerase inhibitor 1 (PinX1) is involved in the development of cancer through angiogenesis." (PMID 35734237, 2022). "Besides increasing sensitivity to DNA damage in cancer cells, PinX1 was also shown to suppress cell cycle progression." (PMID 31210926, 2019). "In addition, silencing PinX1 expression led to a substantial telomere length shortening and growth inhibition in telomerase-positive human cancer cells." (PMID 31210926, 2019). "Therefore, more eligible studies are needed to validate the prognostic value of PINX1 expression in other types of malignant tumors." (PMID 30079348, 2018). "Therefore, we conducted this first meta-analysis to determine the prognostic and clinicopathological value of low PINX1 expression in patients with various types of malignant tumors." (PMID 30079348, 2018). "Hence, we conducted a meta-analysis to increase the sample size and to reduce bias in assessing the prognostic value of PINX1 expression in various types of malignant tumors." (PMID 30079348, 2018). "In addition, low PINX1 expression has been shown to affect chemoradiotherapy sensitivity in cancer cells." (PMID 30079348, 2018). "Therefore, we conducted a meta-analysis of 14 studies containing 2,624 patients to determine the prognostic value of PINX1 expression for survival in patients with malignant tumors." (PMID 30079348, 2018). "However, low PINX1 expression plays various roles in tumor progression and its prognostic value in patients with malignant tumors remains controversial." (PMID 30079348, 2018). "However, cell proliferation in both kidney (HK-2 cell line) and ovarian (SKOV3 cell line) cancer cells transfected with PinX1 siRNA had significantly increased proliferation until 36 h after transfection (P<0.05)." (PMID 28978030, 2017). "Our results indicated that PinX1 deletion is a common genotype in human cancer patients, leading us to believe that insufficient PinX1 may be involved in the progression of a variety of human cancers." (PMID 28978030, 2017). "PinX1 expression was examined using IHC in an NSCLC tissue microarray with 158 cancer samples." (PMID 28815183, 2017). "Moreover, it has been demonstrated that PinX1 is a major haplo-insufficient tumor suppressor gene, stemming from its correlation with chromosome instability and cancer initiation." (PMID 28372542, 2017). "Although there is mounting evidence suggesting PinX1’s role in cancer development and progression." (PMID 28372542, 2017). "PinX1 mRNA expression was decreased in most selected cancer tissues, which could promote tumor growth and enhance tumorigenicity." (PMID 28978030, 2017). "Finally, we selected nine types of cancer samples from our affiliated hospitals to verify their respective PinX1 mRNA expression status." (PMID 28978030, 2017). "We also observed that knockdown of PinX1 could also enhance cell proliferation in nine types of cancer cell lines in vitro." (PMID 28978030, 2017). "We then continued our study in vitro to investigate whether knock-down of PinX1 expression promotes cell proliferation in cancer cell lines." (PMID 28978030, 2017). "PinX1 expression status has been shown to be altered in many cancers." (PMID 28815183, 2017). "PinX1 expression is significantly reduced in a variety of cancer types." (PMID 28815183, 2017). "Then, increasing evidence demonstrate that PinX1 plays a key role in cancer progression." (PMID 27556185, 2016).
cancer (continued). "The mechanism of PinX1 function in human cancer cells has yet to be fully elucidated." (PMID 27556185, 2016). "The functions and the mechanisms of PinX1 in various human cancers remain unclear, suggesting the necessity of further extensive works of its role in tumor genesis and progression." (PMID 27556185, 2016). "It has been identified that Pinx1 deficiency could induce telomerase activation, telomere elongation and chromosome instability, whereas overexpression of PinX1 leads to a decrease in both telomerase activity and cancer cell tumorigenicity." (PMID 25888829, 2015). "Moreover, the role of PinX1 as a putative tumor suppressor was proved by several other groups in different cancer cell lines, such as human breast cancer cells, hepatoma cells, burkitt's lymphoma cells and esophageal epithelial cells." (PMID 26033551, 2015). "Increasing evidence demonstrate that reduced expression of PinX1 promotes cancer progression and propose that PinX1 may be an attractive therapeutic target for human cancers." (PMID 26033551, 2015). "Then, increasing evidence demonstrated that PinX1 plays a key role in cancer progression." (PMID 26033551, 2015). "Two sided Fisher's exact analysis revealed that PinX1 expression in the carcinoma tissues of the training cohort conspicuously correlated with some clinicopathological features, such as depth of invasion-pT status (P = 0.018), lymph node metastasis-pN status (P = 0.043), and TNM stage (P = 0.013)." (PMID 26033551, 2015). "PinX1 knockout in mice can result in embryonic lethality in the PinX1 null mice (PinX1−/−) and the spontaneous development of a variety of malignant tumors in the PinX1 knockout heterozygous mice (PinX1+/−), indicating that PinX1 is a potent telomerase inhibitor and a putative tumor suppressor." (PMID 24672800, 2014). "Moreover, the role of PinX1 as a putative tumor suppressor was proved by several other groups in different cancer cell lines." (PMID 24936151, 2014). "It has been proposed that the PinX1 gene could be a putative tumor suppressor gene and/or therapeutic target for human cancers." (PMID 24268029, 2013). "Disruption of the PinX1-dependent telomere maintenance pathway could reduce carcinogenesis and enhance chemotherapeutic sensitivity in telomerase-positive human cancer cells as well." (PMID 24268029, 2013). "Subsequent PinX1 studies on human cancer samples are inconclusive." (PMID 22021332, 2011). "Moreover, PinX1 inhibition potently increases, whereas PinX1 overexpression suppresses, tumorigenicity of cancer cells." (PMID 22021332, 2011). "Furthermore, PinX1 inhibition in cancer cells activates telomerase and elongates telomeres, whereas PinX1 overexpression has the opposite effects." (PMID 22021332, 2011). "Moreover, telomere lengthening induced by PinX1 inhibition occurs at most chromosome ends, a feature of cancer cells." (PMID 22021332, 2011). "Importantly, PinX1+/- cancer cells also display chromosome instability, similar to those in PinX1-inhibited cells." (PMID 22021332, 2011). "An increasing body of evidence suggests that PinX1 is an attractive new target in cancer therapy." (PMID 22021332, 2011). "Interestingly, overexpression of PinX1 also enhances the sensitivity of human cancer cells to chemotherapy drug 5-fluorouracil." (PMID 22021332, 2011). "Thus, the LPTS/PinX1 protein or its active region may have anticancer effects and is expected to be useful for the treatment of cancer." (PMID 40896430, 2025). "Notably, the deletion of PINX1 exhibited a synergistic effect with PARP inhibition in cancer cells." (PMID 39174499, 2024). "However, the ability of PinX1 to alter the biology of cancer cells needed to be further clarified." (PMID 32028978, 2020). "Our findings suggest that PinX1 may facilitate the invasion and migration of malignant tumors." (PMID 30079348, 2018).
cancer (continued). "Therefore, the precise prognostic role of PINX1 in malignant tumors remains controversial." (PMID 30079348, 2018). "Low PINX1 expression was associated with poor OS and DFS/RFS and lymphatic invasion and advanced tumor-node-metastasis stage, suggesting that PINX1 expression may be a useful predictor of prognosis in patients with malignant tumors." (PMID 30079348, 2018). "Furthermore, the mechanism of PinX1 may change in response to chemoradiotherapy, which may influence the prognosis of patients with malignant tumors." (PMID 30079348, 2018). "However, the tumour-suppressive roles of PinX1 in different types of human cancers are unclear." (PMID 28815183, 2017). "Moreover, emerging evidence suggest that PinX1 (especially its TID domain) might be a potential new target cancer treatment." (PMID 27556185, 2016). "Furthermore, emerging evidence suggest that PinX1 (especially its TID domain) might be a potential new target cancer treatment." (PMID 27556185, 2016). "Thus, LOH seems play a major role in the inactivation of PinX1 in human cancers." (PMID 27556185, 2016). "Notably, PinX1 gene localizes to human chromosome 8p23, which is one of the regions that experiences the most frequent loss of heterozygosity (LOH) in many common human cancers." (PMID 22021332, 2011). "Notably, most tumors in PinX1+/- mice are epithelial carcinomas arising in organs that are known to develop common cancers in humans, including lung, mammary, liver and gastrointestinal tract cancers, which are also known to have frequent LOH at 8p23 in humans." (PMID 22021332, 2011). "Moreover, emerging evidence suggest that PinX1 and especially its small telomerase inhibitory domain might be a potential new drug target for treat cancers that have telomerase activation." (PMID 22021332, 2011). "Moreover, 20% of PinX1+/- mice developed two or three cancer types within the same animals." (PMID 22021332, 2011). "In all 11 cancer cell lines, the level of LPTS/PinX1 protein decreased compared with that in the normal liver cell lines L02 and QSG-7701." (PMID 40896430, 2025). "PinX1, known as a potent TERT inhibitor, also contributes to cellular aging and cancer tumorigenicity." (PMID 35847001, 2022). "However, the role of PinX1 in telomerase/telomere regulation and cancer remains unclear." (PMID 24940406, 2014). "Some cancer-related genes are located in these highly common, early appearing RARs: MCL1, CTSK, ARNT, S100A10, PTK2, PTP4A3, and PSCA in the RAR-Gs; and DLC1, PINX1, and GATA4 in the RAR-Ls." (PMID 22938721, 2012). "However, many questions remained to be addressed including how PinX1 regulates chromosome stability and tumorigenesis, how PinX1 is regulated under physiological and pathological conditions, how to develop PinX1-based cancer therapy, and whether PinX1 has other new functions." (PMID 22021332, 2011). "PinX1 is a TRF-binding protein, and it was reported in various cancers." (PMID 35847001, 2022). "The pooled results of the meta-analysis showed that low PINX1 expression was associated with significantly poorer OS and DFS/RFS, but not DSS, in patients with malignant tumors." (PMID 30079348, 2018). "Therefore, we conducted a meta-analysis to determine whether PINX1 expression is associated with overall survival (OS), disease-specific survival (DSS), disease-free survival (DFS), recurrence-free survival (RFS), and clinicopathological characteristics in patients with malignant tumors." (PMID 30079348, 2018). "It is the first time to validate PinX1 involves in regulating cancer metastasis independent of its ordinary roles like maintaining telomerase activity, the length of telomerase and chromosome stability." (PMID 26033551, 2015).